IL5 (interleukin 5)
Diseases named in the same sentence as IL5 in open-access papers (continued):
Sharing a sentence is not in itself a finding about the gene and the disease.
asthma (continued). "More inflammatory mediators, including cytokines, chemokines, IL-5, and acidity levels, can be measured in the exhaled breath condensate and serve as metabolomic biomarkers of asthma exacerbation in the future." (PMID 38248721, 2023). "The central drivers of T2-high asthma are IL-4, IL-5, and IL-13 that drive airway inflammation through increasing eosinophils, basophils, and mast cells in the airways." (PMID 38259298, 2023). "TSLP, IL-33 and IL-25 are epithelial cell-derived cytokines that stimulate group 2 innate lymphoid cells (ILC2s) to release type 2 cytokines such as IL-5 and IL-13 and play an important role in asthma pathogenesis." (PMID 35292112, 2022). "The final cluster, which was the most saturated with cases of nasal polyps and asthma, had the highest concentration of IL-5 along with high concentrations of IL-6 and IL-8 and had the presence of s." (PMID 36285981, 2022). "TH2 mediators, TNF-α, IL-5, IL-4, IL-1ß play primary role in coordinating various inflammatory mechanisms in asthma." (PMID 38143476, 2022). "Further, many of the prominent underlying pathological features of CRSwNP, including high expression levels of type 2 cytokines (IL-4, IL-5, and IL-13, among others) and elevated IgE, are also key contributors to the pathology of asthma." (PMID 34536215, 2022). "Many mechanisms can sustain corticosteroid resistance in asthma, including an exaggerated production of IL-5 and IL-13, an excessive expression of the dysfunctional GRb isoform, and an impairment of histone deacetylases." (PMID 36140282, 2022). "Th2-driven asthma is the most common and is typically characterized by elevated levels of type 2 inflammatory biomarkers, including type 2 cytokines (e.g., IL-4, IL-5, and IL-13), serum IgE, and blood eosinophils." (PMID 35619697, 2022). "T helper cells are a key regulator during asthma pathogenesis; they regulate the secretion of many cytokines, including IL-13, IL-5 and IL-4 and involved in innate type 2 immunity." (PMID 36201519, 2022). "ROC analysis further demonstrated that NasSec IL-5, NasSec total IgE, comorbid asthma and blood eosinophils counts were good predictors of Th2highCRSwNP." (PMID 36618395, 2022). "Conversely, STAT6 is a transcription factor present in Th2 cells with ability to induce secretion of IL-4, IL-5, and IL-13, which are responsible for the main features of asthma." (PMID 36685604, 2022). "Patients with this profile are the most common participants included in the asthma studies for novel T2‐inflammation focused therapeutics, for example, anti‐IL‐13 and anti‐IL‐5 monoclonal antibodies." (PMID 35305052, 2022). "IL-5 is a cardinal cytokine which regulates miscellaneous features of respiratory track eosinophilic inflammation, which is commonly related to augmented asthma severity, including the promotion of eosinophil’s maturation, activation and survival." (PMID 35743783, 2022). "The cytokines secreted by Th2 cells are mainly IL-4, IL-5, IL-13, and IL-9 which have different roles in the pathogenesis of asthma." (PMID 36032162, 2022). "In this review, especially focused on mepolizumab, we present all current evidence on the indications, use, safety, and efficacy of this fully-humanized anti-interleukin-5 (IL-5) antibody for children with severe asthma." (PMID 35844748, 2022). "In particular, two anti-IL-5 antibodies, Mepolizumab and Reslizumab, and anti-IL-5R antibody, Benralizumab, are approved for severe asthma treatment." (PMID 35408882, 2022). "VD supplementation improved the indicators of asthma and COPD, especially in pulmonary function, SGRQ scores, IL-5, IgE, and IL-10 (in serum VD deficiency group)." (PMID 36520525, 2022). "Targeting BEC reduction through the inhibition of IL-5 represents an established therapeutic option in severe asthma." (PMID 36140430, 2022). "TSLP is crucial for TH2 immunity, which is involved in asthma pathophysiology, as it induces the expression of TH2-associated inflammation drivers, such as IL-4 and IL-5." (PMID 35743783, 2022).
asthma (continued). "Mepolizumab, a humanized monoclonal anti–interleukin (IL)-5 antibody, is effective in cases of severe asthma with a high eosinophil blood count." (PMID 39132061, 2022). "Clinical trials have clearly established that anti-IL5 therapy is effective if the asthma phenotype is driven by luminal eosinophils and that sputum cytometry can reliably identify this subpopulation." (PMID 36237537, 2022). "The release of IL-25 from epithelial cells in asthma also leads to overproduction of IL-4, IL-5, IL-9, IL-13, and CCL11, which then initiate recruitment of eosinophils, DCs, ILC2s, basophils, T cells, and other immune cells." (PMID 36311787, 2022). "The recent introduction of biologic treatments, such as the anti-IgE, anti-IL-5 and anti-IL-4Rα (IL-4/IL-13) monoclonal antibodies have change the management of severe asthma." (PMID 35332239, 2022). "The United States Food and Drug Administration (FDA) approved the first humanized monoclonal antibody, which blocks IL-5 (mepolizumab), to treat the severe asthma eosinophilic phenotype in 2015." (PMID 36497064, 2022). "In asthma, airway inflammation usually involves Th2 cells, which release IL-4, IL-5, IL-9, and IL-13, and play an important role in the development of airway remodeling." (PMID 35419163, 2022). "This study has further demonstrated that with comorbid asthma, the number of blood eosinophils > 0.475*109/L or IL-5 in NasSec > 15.04 ng/mL can be used to define Th2highCRSwNP." (PMID 36618395, 2022). "There are reports to suggest that periostin supports adhesion and migration of IL-5-stimulated human eosinophils and Th2 inflammation in asthma." (PMID 36078171, 2022). "Further analysis on IL-5, IL-13, and IFN-γ levels showed that compared with the normal control, the asthma group had higher IL-5, IL-13 and TNF-α levels and lower IFN-γ levels." (PMID 35210449, 2022). "Biologics like anti-IgE and anti-IL5 monoclonal antibodies are very useful in reducing the frequency of asthma exacerbations." (PMID 35155689, 2022). "Our previous study using a murine model of asthma demonstrated that ILC2s produced more IL-5 in vitro than CD4+ T cells, mainly consisting of Th2 cells." (PMID 36422624, 2022). "Th9 cells and IL-9 promote accumulation and activation of T cells, ILC2s, mast cells, and eosinophils and increase levels of IL-5, IL-13, and IgE in animal asthma models." (PMID 35807067, 2022). "Currently available biologics for severe asthma include the anti-IgE antibody, anti-IL-5 antibody, anti-IL-5 receptor antibody, and human anti-IL-4/13 receptor monoclonal antibody." (PMID 35454111, 2022). "This review describes the IL-5 pathway and presents the clinical trial history of the three IL-5 inhibitors, to provide insight into the role of IL-5 in clinical asthma presentation." (PMID 36232470, 2022). "Similar outcomes were observed in house dust mite- or OVA-challenged asthmatic mice, implying that ILC2 plays a major role in inducing airway inflammation in asthma by enhancing the production of Th2 cytokines, such as IL-5 and IL-13." (PMID 35888038, 2022). "Two types of interleukin (IL)-5 antibody biologics, anti-IL-5 antibodies (mepolizumab) and anti-IL-5α receptor antibodies (benralizumab), are indicated for severe asthma." (PMID 35359852, 2022). "Eosinophils are one of the best-known targets of biological drugs in severe asthma; the well-known role of IL-5 on these cell’s maturation, development and growth led to the choice of this cytokine, or its receptor, as a pharmacological target." (PMID 35455709, 2022). "Aberrant T helper type 2 (Th2) inflammation is the most important pathological process for asthma, which is mediated by Th2 cytokines, such as interleukin (IL)-5, IL-4, and IL-13." (PMID 36078171, 2022). "IL-5 levels were significantly higher in patients with asthma and ABPA than in those with CPA (p < 0.05), and IL-13 levels were significantly higher in patients with asthma than in those with CPA (p < 0.05)." (PMID 35628692, 2022).
asthma (continued). "Low FeNO is also suggestive of infectious exacerbations under anti-IL-5 antibody (mepolizumab) treatment in severe asthma." (PMID 36539765, 2022). "Pulmonary eosinophilia and high amounts of IL-4, IL-5, IL-13 and IgE in the lungs and serum are also characteristic of asthma." (PMID 36145419, 2022). "Previous data reported various cytokines, such as IL-4, IL-5, IL-13, and IL-33, increased in patients with asthma and AR in serum or lower respiratory tract specimens." (PMID 35348596, 2022). "IL-5 has been mainly investigated in asthma and allergic diseases since this cytokine constitutes the most important pathogenic mediator contributing to eosinophilia." (PMID 36361964, 2022). "According to a very recent publication on real-life long-term therapy response to anti-IL-5 biologics in severe asthma, a super-response was observed in 14% of patients." (PMID 35055384, 2022). "Existing clinical data on anti-IgE, anti-IL-5 and other immunological pathways indicate these therapies to offer reduced exacerbation rates, improved lung function, greater asthma control and better quality of life." (PMID 36561741, 2022). "We analyzed the clinical efficacy of anti-IL-5-targeted therapy at approved (benralizumab 30 mg, mepolizumab 100 mg, for severe asthma) and high (benralizumab 100 mg, mepolizumab 300 mg) doses." (PMID 35756113, 2022). "To determine the relationship between PRB1 and type 2‐high asthma further, we detected the levels of IL‐2, IL‐4, IL‐5, IL‐6, IL‐10, IL‐13, IL‐17, and INF‐γ in the induced sputum supernatant." (PMID 35344278, 2022). "Observational studies on type-2 cytokines in sputum also showed that mean IL-4, IL-5, and IL-13 mRNA expression and concentrations of these cytokines were increased in elderly patients with asthma." (PMID 36291665, 2022). "These trials have proved the therapeutic efficacy of anti-IL-5 and anti-IL-5Rα antibodies by reducing annual asthma exacerbations." (PMID 36232470, 2022). "In certain severe asthma conditions, biologics such as omalizumab (anti‐IgE), mepolizumab, reslizumab and benralizumab (anti‐IL‐5 pathways), and dupilumab (anti‐IL‐4/IL‐13) represent major advances in asthma care." (PMID 40496383, 2022). "Th2-mediated inflammatory responses play critical roles in the pathogenesis of asthma by releasing cytokines such as IL-4 and IL-5." (PMID 35040955, 2022). "There was also a reduction in the production of Th2 cytokines (IL-4 and IL-5), a key indicator of asthma-inducing immunology." (PMID 35455087, 2022). "In the cluster analysis of CRS patients based on immunological biomarkers, the high IL-5 clusters showed increased levels of total IgE and SE-IgE in nasal tissues and also a higher frequency of comorbid asthma." (PMID 36159836, 2022). "Secondly, patients with asthma have increased levels of plasma cytokines such as IL-4, IL-5, and IL-13 and chemokines such as monocyte chemoattractant protein-1 (MCP-1)." (PMID 35905078, 2022). "This systematic review provides evidence about the real‐world effects of anti‐IL5 biologicals in asthma." (PMID 35174566, 2022). "Administration of anti-IL-6 antibodies during asthma induction increased IL-13, IL-4, and IL-5 protein levels in the BALF." (PMID 35408882, 2022). "Studies on asthma indicate that inhibiting the production of inflammatory factors, such as IL-1, IL-6, IL-8, IL-4, IL-5, TNF-α, and IFN-γ, can reduce allergic symptoms." (PMID 36307493, 2022). "For severe allergic asthma: omalizumab, for eosinophilic asthma: anti-IL5/anti-IL5 receptor treatment, and for asthma with type 2 inflammation: dupilumab." (PMID 35983568, 2022). "Pediatric asthma is mainly characterized by a T helper type (Th)-2-inflammation in which the release of interleukin (IL)-4, IL-13, IL-5, and the immunoglobulin E (IgE) production increase eosinophilic survival." (PMID 36483465, 2022).
asthma (continued). "On the basis of the recommendations reported in step 5 of GINA (Global Initiative for Asthma) guidelines, currently available biological therapies for severe asthma include anti-IgE, anti-IL-5, anti-IL-5R and anti-IL-4R add-on treatments." (PMID 35625801, 2022). "Our results suggest that circulating ILC2s in patients with asthma are preactivated via the IL-4 receptor signaling pathway and produce IL-5 and IL-13 vigorously by stimulation." (PMID 37779537, 2022). "RV infection induced IL-33 and Th2 cytokine responses in the airways of asthma patients, with IL-33 levels correlating with IL-5 and IL-13 levels." (PMID 36077310, 2022). "Corticosteroids and biological therapies (e.g., anti-IL-4Rα, anti-IL-5/5Rα, and anti-IgE antibodies) have been indicated for asthma treatment in the guidelines of the Global Initiative for Asthma (GINA)." (PMID 35572500, 2022). "In human asthma, we previously observed that after IL5 inhibition with mepolizumab treatment, the number of intact airway eosinophils was strongly reduced, but the airway deposition of toxic proteins (EPX) and free granules was not significantly attenuated." (PMID 35681515, 2022). "It was shown that mast cells produce and release IL-5 in asthma, and that mast cell-released IL-5 contributes to intestinal inflammatory disease." (PMID 35558068, 2022). "Anti-IL-5 and anti-IL-5 receptor antibody treatment significantly decrease the frequency of asthma exacerbations and the use of systemic glucocorticoids, improving lung function and quality of life." (PMID 36497064, 2022). "The biologic drugs currently available (anti-IgE, anti-IL4Rα, anti-IL5, and anti-IL5Rα) for severe asthma are currently undergoing clinical development studies to extend their availability to patients with nasal polyposis." (PMID 35743736, 2022). "The anti-IL-5 antibodies reduce the incidence of exacerbation and allowed steroid sparing in severe asthma patients but only two case reports have been published on their use in critical care." (PMID 36046750, 2022). "In this study, sputum TIPE2 levels were significantly increased in patients with EA and positively correlated with sputum IL-4, IL-5, and IL-13 that promoted eosinophilic inflammation in asthma." (PMID 35572500, 2022). "Low fractional exhaled nitric oxide (FeNO) levels have been described as markers of comorbid bronchiectasis in asthma and infectious exacerbations in patients treated with anti-interleukin (IL)-5 antibody for severe asthma." (PMID 36539765, 2022). "Current treatment guidelines for patients with severe, uncontrolled asthma with eosinophilia recommend anti-IL-5 therapy." (PMID 35203504, 2022). "All children with high TSLP BAL levels (n = 9) were classified as severe asthma and had significantly elevated levels of IL-5 (median values in pg/mL, 0.403 vs. 1.95, p = 0.01)." (PMID 36245744, 2022). "Together, these two pathways lead to differentiation of naive T cells into Th2 cells, releasing a large number of inflammatory factors (IL‐4, IL‐5 and IL‐13) and aggravating the progression of asthma." (PMID 35079347, 2022). "Previously, we successfully established an AD mouse model for the study of asthma and detected elevated levels of IL-4, IL-5, and IgE, confirming the involvement of Th2 inflammation in the progression from AD to asthma." (PMID 35177102, 2022). "Airway smooth muscle cells can also induce a proinflammatory environment in asthma by secreting a myriad of inflammatory cytokines, including a family of interleukins (IL), such as IL-1, IL-5, IL-6, and IL-8, and growth factors, including TGF-β1 and VEGF." (PMID 35888038, 2022). "Similar to patients with severe refractory asthma the ‘asthma/COPD overlap type’ with eosinophilia have been shown to benefit from monoclonal antibody targeted against Interleukin-5." (PMID 35287677, 2022).
asthma (continued). "Research on asthma patients and mice models of the disease has shown that activation of Th2 and production of Th2 type cytokines such as IL-13, IL-4, and IL-5, lead to activation of eosinophils and production of IgE." (PMID 36249456, 2022). "The study included 34 patients with severe asthma treated with anti-IgE (omalizumab, n=17), anti-IL5 (mepolizumab, n=13; reslizumab, n=3), or anti-IL5R (benralizumab, n=1) biological therapy." (PMID 35669765, 2022). "A subsequent meta-analysis about the efficacy of anti-IL5 therapy in patients with asthma confirmed the effects of mepolizumab on S-EOS%." (PMID 36300189, 2022). "Due to its key role in eosinophil development, release and recruitment to tissues, IL-5 has been identified as alongside IL-4 and IL-13 as key cytokines behind the pathophysiology of T2 asthma." (PMID 36232470, 2022). "Patients with childhood asthma have been found to respond better to IgE-targeted therapeutics, while adult-onset asthma patients respond better to anti-IL5 antibodies and therapies." (PMID 36294997, 2022). "IL-5-anchored CCAR-T cells effectively restricted eosinophil differentiation with obvious protection against allergic airway inflammation in murine asthma models." (PMID 35973984, 2022). "In the pooled analysis of the DREAM and MENSA studies, a better response to treatment with the anti-IL5 mAb mepolizumab was observed in patients with severe asthma and BEC of ≥150 cells/μL in baseline." (PMID 36226150, 2022). "Most treatments of the type 2 (T2) target phenotype of asthma, in which IL-4, IL-5, and IL-13 modulate the central signals of inflammatory reactions." (PMID 35327702, 2022). "Asthma is an allergic disease of immune imbalance, and overactivation of Th2 cells is induced in the lung to exacerbate the secretion of IL-4, IL-5, and IL-13 cytokines." (PMID 35682783, 2022). "In support of this, type 2–high asthma is characterized by elevated levels of IgE and Th2 cytokines, including IL-4, IL-5, and IL-13." (PMID 34536215, 2022). "Asthma is characterized by chronic airway inflammation, in which Th2 cells promote the accumulation of eosinophils by secreting interleukin IL-4, IL-5, and IL-13 is the key pathogenesis of asthma." (PMID 35287655, 2022). "In the early efficacy studies of the anti-IL5 mAb reslizumab, significant reductions in asthma exacerbation rate and improvements in lung function were observed in patients with persistent asthma and BEC ≥400 cells/μL." (PMID 36226150, 2022). "In conclusion, IL-5 and GM-CSF demonstrated a significant effect on the proliferative properties of eosinophil subtypes in patients with asthma; the exposure of these eosinophilopoetins to eosinophil subtypes significantly increased the ASM cell number." (PMID 36497064, 2022). "Mepolizumab and reslizumab, monoclonal anti-IL-5 antibodies, and benralizumab, which targets IL-5Rα, are approved for the treatment of asthma and have shown to improve allergic asthma." (PMID 36389745, 2022). "The pathogenesis of asthma is mainly mediated by type-2 inflammation, with increased production of Th2 cytokines such as IL-4, IL-5, and IL-13 by Th2 cells and ILC2s." (PMID 35625578, 2022). "Asthma pathogenesis is strongly influenced by a number of mediators of inflammation, such as IgE, IL-3, IL-4, IL-5, IL-9, IL-13, IL-33 and TSLP, with many more being discovered." (PMID 36561741, 2022). "The current therapeutic approach for Th2-high severe asthma is based on biologics targeting allergy molecules (IgE) and eosinophilic interleukins (IL-5, IL-4, IL-13, TSLP)." (PMID 35887589, 2022). "Mepolizumab is a fully humanized recombinant IgG1 kappa monoclonal antibody against IL5, and has been approved for severe asthma." (PMID 36009493, 2022). "Despite their comparable effects, anti-IL-5 and anti-IL-5Rs have different mechanisms of action, and their effects vary depending on specific asthma endotypes." (PMID 35887589, 2022).